KDM1A (lysine demethylase 1A)
Diseases named in the same sentence as KDM1A in open-access papers (continued):
Sharing a sentence is not in itself a finding about the gene and the disease.
Glucose intolerance (2 papers, 2021 to 2022). Glucose intolerance (GI) can be defined as dysglycemia that comprises both prediabetes and diabetes. "IPA suggested four upstream regulators that could be linked to glucose intolerance: interleukin 6 (IL6), tuberous sclerosis complex 2 (Tsc2), peroxisome proliferator-activated receptor gamma coactivator 1-beta (Ppargc1b), and lysine (K)-specific histone demethylase 1A (Kdm1a)." (PMID 35377872, 2022).
helminth infection (2 papers, 2021). "KDM1A is also important for goblet cell maturation and effector responses of gut immunity to bacterial and helminth infections." (PMID 34925656, 2021).
Intellectual disability (2 papers, 2017 to 2024). "Kdm1a is a histone demethylase linked to intellectual disability with essential roles during gastrulation and the terminal differentiation of specialized cell types, including neurons, that remains highly expressed in the adult brain." (PMID 38453932, 2024).
malignant glioma (2 papers, 2018 to 2024). A grade III or grade IV glioma arising from the central nervous system. "Lysine-specific demethylase 1 (LSD1/KDM1A) is a pivotal epigenetic enzyme that contributes to several malignancies including malignant glioma." (PMID 39501082, 2024).
mastitis (2 papers, 2023 to 2024). Inflammation of breast tissue during lactation or postpartum due to an obstructed duct or infection. "The clinically explored KDM1A inhibitor GSK-LSD1 has been reported to inhibit the NF-κB-dependent production of cytokines (TNFα, IL-6, IL-1) by increasing histone H3K4me2 and H3K9me2 in LPS-induced mastitis." (PMID 39638799, 2024).
ovarian clear cell cancer (2 papers, 2022 to 2024). An invasive malignant neoplasm that arises from the ovary and is characterized by a predominance of clear and hobnail malignant epithelial cells. "LSD1/KDM1A inhibition induces the expression of CD8+ T-cell-attracting chemokines in TNBC cell lines and stimulates IFN-dependent antitumor immunity in ovary hypercalcemic-type (SCCOHT) cell lines, promoting PDL1 expression in SCCOHT and ovarian clear cell carcinoma (OCCC) cells." (PMID 38612726, 2024).
parasitic infection (2 papers, 2021 to 2025). "KDM1A can impact viral and parasitic infections via the epigenetic regulation of viral genes and immune response." (PMID 34925656, 2021).
adrenal hyperplasia (1 paper, 2024). "Genetics: It is now clear that there are no KDM1A (lysine demethylase 1A) germline mutations in acromegalic patients, like in gastric inhibitory polypeptide (GIP, alternatively named glucose-dependent insulinotropic polypeptide)-dependent primary bilateral macronodular adrenal hyperplasia." (PMID 39194755, 2024).
adult glioblastoma (1 paper, 2025). "Lysine-specific demethylase 1 (LSD1/KDM1A) is a histone demethylase that has been identified as a potential therapeutic target in HGG, including adult glioblastoma." (PMID 41497449, 2025).
carotid atherosclerosis (1 paper, 2023). A thickening and loss of elasticity of the walls of carotid arteries that occur with formation of atherosclerotic plaques. "The present study sought to delineate the effect of the interaction between lnc_000048 and KDM1A on plaque rupture in carotid atherosclerosis, as well as the potential mechanism." (PMID 36689133, 2023).
folate deficiency (1 paper, 2025). A nutritional condition produced by a deficiency of FOLIC ACID in the diet. "Mouse postnatal paternal folate deficiency alters H3K4me3 at developmental loci in sperm, and folate deficiency in KDM1A transgenics mouse increases sperm H3K4me3 levels and the likelihood of birth defects." (PMID 41266313, 2025).
glomerulosclerosis (1 paper, 2026). A hardening of the kidney glomerulus caused by scarring of the blood vessels. "We used Kdm1a-KO mice to demonstrate that Kdm1a depletion in nephron progenitor cells results in reduced kidney size in neonates and led to glomerulosclerosis, proteinuria, and renal cysts in adults." (PMID 41797715, 2026).
mesothelioma (1 paper, 2021). A usually malignant and aggressive neoplasm of the mesothelium which is often associated with exposure to asbestos. "It is worth mentioning that deep deletion of KDM1A accounted for all cases of genetic alteration in CHOL, pheochromocytoma and paraganglioma (PCPG), DLBC, mesothelioma (MESO), THYM, TGCT, and KIRC." (PMID 34925656, 2021).
monoclonal gammopathies (1 paper, 2022). "It has been described that those patients with KDM1A mutations have a higher risk of developing monoclonal gammopathies, so it is recommended to perform a serum protein electrophoresis study in all patients with KDM1A mutations." (PMID 35992106, 2022).
neural tumors (1 paper, 2016). "KDM1A has been implicated in several cancer types, particularly neural tumors." (PMID 27449289, 2016).
neuroendocrine prostate tumors (1 paper, 2020). "Furthermore, the role of SOX2 has been reported in repressing adenocarcinoma specific genes by enhancing the expression and activity of lysine-specific demethylase 1A (LSD1/KDM1A), highlighting the potential of SOX2 as a lineage reprogramming factor in neuroendocrine prostate tumors." (PMID 32754615, 2020).
Noonan syndrome (1 paper, 2023). Noonan Syndrome (NS) is characterized by short stature, typical facial dysmorphism and congenital heart defects. "In Noonan syndrome, KDM1A could affect the histone methylation level of the MAP2K2 promoter region." (PMID 36689133, 2023).
schwannoma (1 paper, 2024). A benign, usually encapsulated slow growing tumor composed of Schwann cells. "Transwell migration assays showed conditioned media from schwannoma cells recruited primary human peripheral blood lymphocytes after radiotherapy, and conditioned media from schwannoma cells with CRISPRi suppression of the radiotherapy resistance hit KDM1A enhanced lymphocyte migration." (PMID 38216587, 2024).
somatotropinomas (1 paper, 2023). "Investigating, for instance, the presence of somatic alterations in KDM1A and their functional effects on GIPR expression, and more in general on the transcriptional profile of somatotropinomas, could be a promising target for short-term studies." (PMID 37298217, 2023).
steatosis (1 paper, 2024). Increased lipid within the cytoplasm of cells. "Mechanistically, we found that Kdm1a deficiency led to an improvement in hepatic steatosis and inflammation by decreasing the chromatin openness in regions where genes associated with inflammation, lipid metabolism, and glucose metabolism are located." (PMID 38295985, 2024).
teratoma (1 paper, 2018). A non-seminomatous germ cell tumor characterized by the presence of various tissues which correspond to the different germinal layers (endoderm, mesoderm, and ectoderm). "In the present study, we used gain-of-function and loss-of-function approaches to determine that expression of lysine-specific demethylase 1 (LSD1/KDM1A) is elevated in hiPSC-derived teratomas and that LSD1 deregulation underlies teratoma development." (PMID 29464084, 2018).
cancer (548 papers, 2008 to 2026). A tumor composed of atypical neoplastic, often pleomorphic cells that invade other tissues. "Since the discovery of LSD1 (KDM1A), which demethylates H3K4me1/2 and H3K9me1/2, many KDMs have been characterized and linked to cancer pathogenesis." (PMID 40508013, 2025). "KDM1A/LSD1 is known to be overexpressed in a wide variety of cancers and is associated with promoting cancer cell progression." (PMID 40559396, 2025). "The processes to which KDM1A activity has been linked and its prominent dysregulation in human cancers make it an attractive therapeutic target." (PMID 39458030, 2024). "LSD1 (also known as KDM1A) is a well-known histone demethylase that has been implicated in cancer phenotypic plasticity." (PMID 40994652, 2024). "Evidence showed that the upregulation of KDM1A is associated with multiple human disorders, such as cancer, through reduced methylation at the H3K4 and H3K9." (PMID 37046703, 2023). "By analyzing the age‐associated genes and common cancer targets prioritized by AI, we predicted a list of potential dual‐purpose candidates and validated an unreported dual‐purpose candidate, KDM1A (lysine‐specific demethylase 1A), in C. elegans." (PMID 37888486, 2023). "Various algorithms in TIMER2.0 were applied to measure the potential correlation between KDM1A and cancer-associated fibroblast (CAF) and immune cells in diverse cancer types." (PMID 34925656, 2021). "KDM1A expression was positively correlated with the cancer-associated fibroblasts and myeloid-derived suppressor cells infiltration levels in most cancer types." (PMID 34925656, 2021). "The current evidence suggested that KDM1A plays different roles in diverse cancers, and the underlying molecular mechanisms that occur in several cancers merit further investigation." (PMID 34925656, 2021). "We applied cBioPortal to observe the chromosomal abnormalities and mutation status of KDM1A in various cancers using the TCGA data." (PMID 34925656, 2021). "Our analysis observed a statistically positive correlation between KDM1A expression and cancer-associated fibroblasts in most cancer types via multiple algorithms." (PMID 34925656, 2021). "KDM1A has also been associated with the development of a variety of pathological conditions, such as cancer, neuronal disorders, and viral infections." (PMID 29921310, 2018). "Although epigenetic loss of miR137 contributes to increased KDM1A expression in colo-rectal and oral cancers respectively, the mechanisms resulting in increased KDM1A and NCOA2 in PCa cells are not well understood." (PMID 26461474, 2015). "The aberrant amplification and function of lysine‐specific histone demethylase LSD1 (KDM1A), implicated in the progression of cancer, has sparked interest due to its role in transcriptional repression through the removal of methylation from H3K4me1/2, a marker of gene activation." (PMID 38374872, 2024). "Importantly, in human cells, KDM1A inhibition causes TE reactivation, which in turn triggers an immune response that renders cancer cells more susceptible to immunotherapy." (PMID 36010577, 2022). "Altered KDM1A expression is associated with tumorigenesis and is upregulated in various cancers." (PMID 35454810, 2022). "High KDM1A expression was associated with worse survival status in various cancers." (PMID 34925656, 2021). "Furthermore, we investigated the association between the clinical survival of cases and KDM1A mutations with various cancers." (PMID 34925656, 2021). "KDM1A, with the highest activation z-score, encodes lysine demethylase 1, which contributes to tumorigenesis in many types of cancer, while TP63 encodes p63 protein which is a master regulator in epithelial development and has shown significance in cancer progression." (PMID 31877723, 2019). "High KDM1A expression has been implicated in cancer development and cancer progression." (PMID 31649884, 2019).
cancer (continued). "KDM1A also interacts with estrogen receptor alpha (ERα), which is associated with estrogen signaling in estrogen-responsive tissues, and any impairment in its function can lead to the genesis and progression of various types of cancers." (PMID 29921310, 2018). "Moreover, deficiency in this histone demethylase (KDM1A) is implicated in cancer and embryonic stem cell differentiation." (PMID 28234898, 2017). "To test whether KDM1A-deficient cancer cells show decreased methylation of repetitive sequences, we used pyrosequencing to quantify the methylation of interspersed (LINE1) and tandem repeats (D4Z4, NBL2)." (PMID 27449289, 2016). "Among the most important histone demethylases associated with the development of cancer are LSD-1/KDM1A, and members of the Jumonji family JARID1A-1C/KDM5A-5C, JHDM1B/KDM2B, JMJD2C/KDM4C, JMJD2A/KDM4A, JMJD3/KDM6B, and UTX/KDM6A, which will be analyzed in detail in the following paragraphs." (PMID 24280700, 2012). "In addition, not only is there a strong association between aberrant KDM1A expression and the development of various types of cancer, but analysis of clinical data also suggests that KDM1A expression is closely associated with tumor lymph node staging, distant metastasis and poor prognosis." (PMID 40600050, 2025). "However, the regulatory network of miR-506-3p in cancer is of considerable relevance in tumor prevention and treatment, thus further studies are required to reach a more exhaustive understanding of its association with KDM1A." (PMID 37385999, 2023). "There are also several KDM1A dual inhibitors being developed that hold promise for dual-targeting therapies, targeting other epigenetic factors or drivers of cancer, such as EGFR." (PMID 40805121, 2025). "Lysine-specific demethylase 1 (LSD1), encoded by the KDM1A gene, is a lysine demethylase intricately linked to malignant transformation, EMT, cell proliferation, and differentiation across various cancers, making it a critical target for cancer therapies." (PMID 41220942, 2025). "Knock-out of KDM1A (KDM1A-KO) or treatment with KDM1A demethylase inhibitors resulted in the up-regulation of REST along with the suppression of cancer cell growth." (PMID 40006989, 2025). "STAT3 protein levels were significantly higher in cancer cells than in normal epithelial cells and were significantly reduced in cancer cells when KDM1A was knocked out using the CRISPR-Cas9 system." (PMID 40246812, 2025). "Our understanding of how histone methylation occurs during both normal biological processes and cancer was fundamentally altered by LSD1 (also known as KDM1A)." (PMID 39991574, 2025). "At present, a number of studies on KDM1A inhibitors in the treatment of malignant tumors have made progress." (PMID 40164592, 2025). "Increased levels of KDM1A have been reported in multiple cancers, including ESCC, thus igniting explorations of its inhibitors for targeted therapies." (PMID 39638799, 2024). "Lysine-specific demethylase 1 (LSD1, also known as KDM1A, AOF2, and BHC110) is ubiquitously overexpressed in diverse cancers, and abrogation of LSD1 expression inhibits the proliferation, invasion, and migration of cancer cells." (PMID 39872520, 2024). "In a screen of cell lines representing various cancer types with a lysine demethylase 1A (LSD1) inhibitor, SCLC was identified as the most sensitive cancer type, with DNA hypomethylation signature acting as a biomarker for sensitivity." (PMID 39456533, 2024). "Lysine-specific demethylase 1 (LSD1/KDM1A) and histone deacetylases(HDACs) have been exhaustively explored as epigenetic targets forthe design of cancer therapeutics in the past decade." (PMID 39320444, 2024). "Lysine-specific demethylase 1 (LSD1), also known as KDM1A, plays crucial roles in cancer initiation, progression, metastasis, and recurrence by removing lysine methylation marks from nucleosome histone tails." (PMID 39519018, 2024).
cancer (continued). "KDM1A, a well-established oncogene, exhibits high expression in multiple cancers and correlates with unfavorable prognosis in cancer patients." (PMID 38965210, 2024). "KDM1A is highly expressed in various human cancers, such as triple-negative breast cancer and cancer stem cells (CSCs)." (PMID 39239542, 2024). "Next, Venn analysis showed that 56 genes were simultaneously upregulated in KDM1A deficient TE1 and K410 cells, which were subjected to GSEA enrichment of cancer hallmarks and heatmap analysis." (PMID 39638799, 2024). "Histone lysine demethylase LSD1, also known as KDM1A, has been found to regulate multiple cancer hallmarks since it was first identified in 2004." (PMID 39638799, 2024). "After demonstrating specificity for KDM1A and anti-cancer and pro-differentiation activities in preclinical models, a total of nine LSD1 inhibitors have entered clinical trials for hematological and/or solid cancers." (PMID 39458030, 2024). "KDM1A is overexpressed in several cancers, where it inhibits cell differentiation while enhancing cell proliferation and aggressiveness." (PMID 37385999, 2023). "KDM1A expression is frequently increased in various malignancies, and its upregulation is thought to induce cancer cell proliferation, and migration." (PMID 37587156, 2023). "Chemical inhibition experiments have shown that KDM1A is not only involved in the control of cancer, but also in the modulation of metabolic properties by regulating the expression of genes involved in cellular energy expenditure and oxidative metabolism." (PMID 36975603, 2023). "Given KDM1A's anti‐cancer activities reported in both preclinical and clinical studies, our findings propose KDM1A as a promising dual‐purpose target." (PMID 37888486, 2023). "Extensive research into a range of KDM1A inhibitors is currently underway, with rigorous clinical evaluations, highlighting their potential as promising candidates for cancer therapy." (PMID 37958805, 2023). "An API against cancer is the lysine-specific histone demethylase-1A (LSD1 or lysine demethylase 1A, KDM1A) inhibitor GSK-2879552." (PMID 35408960, 2022). "As the anticancer effect of Arborinine and its potential target Lysine Demethylase 1A (KDM1A or LSD1) have been reported in multiple types of cancer, simply validating such effect and signaling in ccRCC are predictable." (PMID 36185617, 2022). "We found that the protein expression of KDM1A was higher in cancer tissues than in normal tissues, especially in ATCs." (PMID 35198054, 2022). "Many of these demethylases have been involved in cancer, such as KDM1A, related to the maintenance of clonogenicity and the inhibition of differentiation." (PMID 35480330, 2022). "Of note, all those cancer researches indicate that Arborinine exerts anticancer effect via inhibiting the KDM1A (or LSD1) activity, which was also corroborated in ccRCC as reported in the current study." (PMID 36185617, 2022). "Emerging reports have demonstrated that KDM1A is commonly dysregulated in a variety of cancers, suggesting KDM1A as a probable biomarker for cancer development and treatment." (PMID 36357457, 2022). "As an important epigenetic enzyme, lysine specific demethylase 1 (LSD1/KDM1A) plays a key functional role in mediating cancer cell death." (PMID 36357457, 2022). "Glycogen synthase kinase‐3β (GSK3β) phosphorylates KDM1A serine 683 (Ser683) upon priming by CK1α, leading to the stabilization of KDM1A, which, in turn, leads to cancer stem cell self‐renewal and GBM tumorigenesis." (PMID 37786890, 2022). "The overexpression of KDM1A has been documented in a variety of cancers, and KDM1A inhibitors have, thus, entered clinical trial." (PMID 36185617, 2022). "Many studies have been devoted to seeking highly selective and active inhibitors targeting KDM1A as antineoplastic drugs due to its multiple carcinogenic effects in various cancers 38-40." (PMID 35198054, 2022).